HMGB1 (high mobility group box 1)
Diseases named in the same sentence as HMGB1 in open-access papers (continued):
Sharing a sentence is not in itself a finding about the gene and the disease.
periodontitis (continued). "This indicates that anti-HMGB1 antibody inhibits not only aggravation of inflammatory diseases such as periodontitis, but also inhibits initial acute inflammation, which is essential for tissue repair." (PMID 32760399, 2020). "High levels of HMGB1 have been reported in the gingival crevicular fluid and inflamed gingiva of periodontitis patients." (PMID 30814594, 2019). "HMGB1 is a mediator factor newly identified to be related to the onset and progress of periodontitis." (PMID 28765610, 2017). "In an experimental periodontitis model, the expression profile of HMGB1 has been shown to be similar to those of TNF-α and IL-6, with higher expression of those cytokines occurring at day 7 and 15 followed by a decrease on day 3012." (PMID 28765610, 2017). "Only a few studies have investigated the role of HMGB1 in the pathological process of periodontitis." (PMID 28765610, 2017). "The in vitro model demonstrated that HMGB1 is expressed and released by PDL fibroblasts upon inflammatory signals, demonstrating the participation of HMGB1 in response to putative inflammatory signals from periodontitis." (PMID 24692854, 2014). "These in vivo results corroborate also with a clinical study that have demonstrated high levels of HMGB1 in gingival tissues and gingival crevicular fluid of chronic periodontitis patients compared to control." (PMID 24692854, 2014). "For example, the dysregulated expression of miR-205 and high-mobility group box 1 (HMGB1) is strongly correlated with the pathogenesis of chronic periodontitis and may serve as potential biomarkers for disease diagnosis and therapeutic monitoring." (PMID 41542727, 2026). "Thus, infection and inflammation promote HMGB1 secretion from periodontal tissue, which further promotes pro-inflammatory cytokine production and osteoclast generation, aggravating periodontitis." (PMID 35572583, 2022). "Elevated concentrations of HMGB1 in the gingival crevicular fluid were observed in periodontitis patients, with significant positive correlations between these HMGB1 levels and all periodontal parameters, including plaque index, bleeding index, probing depth, and clinical attachment level." (PMID 35572583, 2022). "Thus, subsequent studies should focus on improving the understanding of the biological effects of different isoforms of HMGB1 and different receptors in periodontitis." (PMID 32760399, 2020). "HMGB1 was detected at high levels in gingival crevicular fluid (GCF) in periodontitis patients." (PMID 32760399, 2020). "Another study reported that HMGB1 was dislocated from the nucleus of the cells in the pocket epithelium, which faces the infected root surface, but it was mainly localized in the nucleus in the gingival epithelium of periodontitis patients." (PMID 32760399, 2020). "However, the mechanism by which HMGB1 participates in periodontitis and peri-implant disease is still unclear." (PMID 28765610, 2017). "Thus, the aim of this study was to investigate in vitro the expression profile of HMGB1 in mouse periodontal ligament fibroblasts (mPDL) stimulated with Escherichia coli LPS or IL-1β, mimicking the inflammatory condition present in periodontitis." (PMID 24692854, 2014). "This study evaluated changes in inflammatory markers within GCF, including TNF-α, IL-1β, IL-6, IL-8, hs-CRP, ICAM-1, HMGB1, and PGE2, before and after treatment in patients with osteoporosis and periodontitis." (PMID 39686428, 2024). "A number of these genes were also significantly increased in aging and periodontitis tissues (e.g., ANXA1, HMGB1, S100A8, S100A9, APOE/ß2-GPI, LTF, TSLP)." (PMID 38098978, 2023). "In fact, human periodontal ligament cells (HPDL cells) collected from patients with chronic periodontitis had higher levels of inflammatory cytokines, including IL-6, TNF-α, and HMGB-1, than HDPL cells collected from healthy individuals." (PMID 36163018, 2022). "The HMGB1/RAGE/NF-κB signaling also contributed to neuroinflammation and periodontitis in diabetic mice." (PMID 34573077, 2021).
periodontitis (continued). "Among the PRG pairs, HMGB1 and SCAF11 showed the strongest positive correlation in periodontitis." (PMID 35844512, 2022). "In fact, the concentration of HMGB1 (a well-known DAMP) in gingival crevicular fluid (GCF), as well as the number of HMGB1-positive cells are higher in the inflamed gingival epithelium of patients with periodontitis than that of healthy subjects." (PMID 34063235, 2021). "High mobility group box 1 protein (HMGB1) is a non-histone DNA-binding protein that is secreted in various inflammatory diseases such as periodontitis." (PMID 34445604, 2021). "In the oral cavity, higher expression of HMGB1 was detected in gingival tissues and gingival crevicular fluid (GCF) of patients with periodontitis and peri-implantitis, which was accompanied by the elevated concentrations of pro-inflammatory cytokines, such as IL-1β, IL-6, and IL-8." (PMID 34573077, 2021). "An antibody against high mobility group box 1 (HMGB1), a nonhistone DNA-binding protein that is secreted into the extracellular matrix in response to inflammation, suppresses the progression of periodontitis through an antiresorptive mechanism." (PMID 33187558, 2020). "Several studies have investigated the role of HMGB1 in the dental area; however, most of them have investigated its role in periodontitis rather than in peri-implant disease." (PMID 28765610, 2017).
neuroblastoma (25 papers, 2007 to 2025). Neuroblastoma (NB) is the most common solid, extracranial childhood tumor. "In fact, in NB, long non-coding RNA (lncRNA) neuroblastoma highly expressed 1 (NHEG1) negatively regulates the activity of miR-665, which cannot inhibit high mobility group box 1 (HMGB1) expression, causing the aggressive phenotype of neuroblastoma cells." (PMID 39202438, 2024). "In neuroblastoma, miR-665 acts as a tumor suppressor by inhibiting HMGB1 and thus blocking the Wnt/β-catenin pathway." (PMID 37894282, 2023). "LncRNA NHEG1 has multiple MREs for miR-665 and can thus inhibit HMGB1, thereby suppressing neuroblastoma cell proliferation, migration, and invasion." (PMID 37894282, 2023). "MiR-665 acts as a tumor-suppressive microRNA in neuroblastoma by directly targeting high mobility group box 1 (HMGB1) (activator of the Wnt/β-catenin pathway) and thus inactivating the Wnt/β-catenin pathway." (PMID 37894282, 2023). "LncRNA neuroblastoma highly expressed 1 (NHEG1) increased high mobility group box 1 (HMGB1) expression by sponging miR-655 to promote neuroblastoma progression." (PMID 35030969, 2022). "Together, our data demonstrated that lncRNA NHEG1 serves as a competitive partner to negatively regulate the activity of miR-665, which relieves the inhibition on HMGB1 expression and promotes the aggressive phenotype of neuroblastoma cells." (PMID 34889712, 2021). "Autophagy induced by HMGB1 overexpression in Schwann cells also contributes to the proliferation of neuroblastoma cells, suggesting a role of HMGB1 in neuroblastoma and its potential as a therapeutic target." (PMID 33140586, 2021). "HMGB1 overexpression also contributed to the chemoresistance of neuroblastoma cells by inducing Beclin-1-mediated autophagy." (PMID 28938696, 2017). "We have demonstrated that targeting of tumor-derived endothelial cells with an anti-human CD31 monoclonal antibody in a human neuroblastoma model was unsuccessful due to a complex chain of events involving the participation of HMGB1." (PMID 26925422, 2016). "On the basis of these observations, here we have explored the effect of HMGB1 on nerve terminals isolated from rat hippocampus and on human neuroblastoma cells expressing functional NMDARs and stimulated with sub-optimal concentrations of NMDA." (PMID 22952988, 2012). "An alternative cell model that we have selected to investigate the possible functional effects of HMGB1 on NMDAR is the human neuroblastoma SK-N-BE cell line." (PMID 22952988, 2012). "An early event promoted by HMGB1/NMDAR interaction in neuroblastoma cells is an increase in the level of [Ca2+]i mediated by activation of the ionotropic receptor." (PMID 22952988, 2012). "At a functional level, these HMGB1-dependent changes result in an increased neuroblastoma cell motility and neurite outgrowth, both processes known as positively affected by Ca2+, NO and HMGB1." (PMID 22952988, 2012). "LncRNA NHEG1 could sponge miR-665 which inhibits HMGB1 that promotes neuroblastoma, so neuroblastoma tumor progression is upregulated by the lncRNA NHEG1." (PMID 37894282, 2023). "Our study indicates that lncRNA NHEG1/miR-665/HMGB1 axis may play an important role in regulating the aggressiveness and the progression of neuroblastoma." (PMID 34889712, 2021). "Our study suggests that lncRNA NHEG1/miR-665/HMGB1 axis may play an important role in regulating the aggressiveness and progression of neuroblastoma." (PMID 34889712, 2021). "In addition, HMGB1 inhibited PTEN by upregulating the miR‐221/222 cluster in neuroblastoma cell lines to induce a malignant phenotype." (PMID 33140586, 2021). "Other similar works found that extracellular HMGB1 can act extrinsically on its membrane receptor TLR-4 to facilitate the signaling of pro-survival factors in neuroblastoma, and HMGB1/TLR-4 signaling would be activated to inhibit cell apoptosis in cortex of rats with brain injury." (PMID 32708917, 2020).
neuroblastoma (continued). "In addition, doxorubicin, cisplatin and etoposide induced the expression and cytosolic translocation of HMGB1 to elevate autophagy level of neuroblastoma cells." (PMID 28938696, 2017). "Emerging evidence also suggests that HMGB1 contributes to resistance against monoclonal antibody–based immunotherapies, such as anti-CD31 treatment in neuroblastoma, where HMGB1-driven signaling undermines therapeutic efficacy." (PMID 41465435, 2025). "Here we demonstrate that, at concentrations of agonist per se ineffective, HMGB1 potentiates the activation of the ionotropic glutamate N-methyl-D-aspartate receptor (NMDAR) in isolated hippocampal nerve terminals and in a neuroblastoma cell line." (PMID 22952988, 2012). "HMGB1 was released from neuroblastoma cells but not from normal cells after 131I-MIBG administration." (PMID 40583575, 2025). "Notably, HMGB1 plays a critical role in promoting RAGE-dependent neuronal differentiation in cultured neural progenitor cells and neuroblastoma cells." (PMID 32708917, 2020). "To confirm the effect of Regnase-1 on regulating neuronal survival during HMGB1-mediated inflammation, we finally added BV2 CM to SH-SY5Y cells, a neuroblastoma cell line with neuron-like properties, followed determination of neuronal cell toxicity and activity." (PMID 27044405, 2016). "The HMGB1-facilitated NMDAR opening was followed by activation of the Ca2+-dependent enzymes calpain and nitric oxide synthase in neuroblastoma cells, resulting in an increased production of NO, a consequent enhanced cell motility, and onset of morphological differentiation." (PMID 22952988, 2012).
chronic kidney disease (23 papers, 2011 to 2025). Impairment of the renal function secondary to chronic kidney damage persisting for three or more months. "Chronic kidney disease (CKD) also bears a strong association with HMGB1-elevated serum levels and decreases in estimated glomerular filtration rate (eGFR), being some of the hallmarks of CKD patients as well as in ambulatory peritoneal dialysis patients." (PMID 39682695, 2024). "Elevated levels of HMGB1 were found in patients with chronic kidney diseases, and HMGB1 has been detected in urine, blood, and cell types of renal parenchyma in renal disease conditions." (PMID 34204735, 2021). "However, when a septic episode complicates a long-lasting chronic kidney disease, HMGB1 is an early appearing cytokine measured in the plasma within 6 h in mice with septic condition due to CLP." (PMID 33732235, 2021). "An increased serum HMGB1 level is observed in febrile seizures and end stage renal disease." (PMID 34299145, 2021). "Elevated serum levels of HMGB1 have been found in different inflammatory conditions such as sepsis, rheumatoid arthritis, anti-neutrophilic cytoplasmatic antibody (ANCA)-associated vasculitis, and chronic kidney disease as well as in SLE." (PMID 22348591, 2012). "In chronic kidney disease, HMGB1 has been shown to correlate with renal function." (PMID 21548924, 2011). "Recently, benidipine was shown to reduce the circulating levels of inflammatory cytokines or proteins, such as IL-6 and high mobility group box-1 (HMGB-1), in patients with chronic kidney disease." (PMID 25866450, 2015). "Although HMGB1 levels have been shown to correlate inversely with renal function in patients with chronic kidney disease, no such correlation was found in our study or in the previous study of patients with SLE." (PMID 22348591, 2012).
chronic obstructive pulmonary disease (23 papers, 2013 to 2025). A chronic and progressive lung disorder characterized by the loss of elasticity of the bronchial tree and the air sacs, destruction of the air sacs wall, thickening of the bronchial wall, and mucous accumulation in the bronchial tree. "HMGB1 activates Aspergillus fumigatus in alveolar macrophages in chronic obstructive pulmonary disease through the MyD88/NF-κB and syk/PI3K signal transduction pathways, leading to inflammation." (PMID 33979394, 2021). "In another large study comprising 145 NSCLC patients, cancer patients had significantly higher HMGB1 levels when compared to 77 patients with chronic obstructive lung disease and 49 healthy individuals." (PMID 33672622, 2021). "High‐mobility group box 1 (HMGB1) shows pro‐inflammatory activity in various inflammatory diseases and has been found up‐regulated in chronic obstructive pulmonary disease (COPD)." (PMID 31769590, 2020). "An elevated HMGB1 expression has been identified in smokers with chronic obstructive pulmonary disease (COPD)." (PMID 31011483, 2019). "Previous studies suggest that HMGB-1 is involved in a variety of biological processes and is linked to a wide range of human diseases, such as diabetes, asthma, and chronic obstructive pulmonary disease (COPD)." (PMID 30558126, 2018). "HMGB1 mRNA and protein expressions were identified to be positively correlated with NFκB protein expression in a rat model of chronic obstructive pulmonary disease." (PMID 23956502, 2013). "Accordingly, high levels of HMGB1 as well as negative correlation between HMGB1 levels and lung function have been described in the context of chronic respiratory diseases, such as chronic obstructive pulmonary disease (COPD) and cystic fibrosis." (PMID 36071400, 2022).
diabetic retinopathy (23 papers, 2012 to 2025). "Recent reports suggested that HMGB1 causes impairment of autophagy by inducing lysosomal membrane permeabilization (LMP) in diabetic retinopathy." (PMID 37038107, 2023). "To investigate the pathogenic functions of HMGB1 in diabetic retinopathy, we initially used immunohistochemistry to determine whether the HMGB1 protein is expressed in the retina." (PMID 26950148, 2016). "These molecules are expressed in different eye diseases, and diabetic retinopathy; the predominant DAMPs are S100, HMGB1, uric acid, HSPs, ATP, cyclophilin A, Aβ, IL 1-α, IL-33, nuclear DNA, mtROS, formyl peptide, and lipid from the mitochondrial membrane." (PMID 36678750, 2022). "In diabetic neuropathy, HMGB1 increases NFκB activity, while in diabetic retinopathy, HMGB1 has been shown to upregulate NFκB specifically by inhibiting the activity of IKB-α." (PMID 35573828, 2022). "Summary of direct and indirect high-mobility group box (HMGB1) inhibitors with therapeutic potential in diabetic retinopathy." (PMID 32722545, 2020). "Under diabetic environment, HMGB-1 acts as a proinflammatory cytokine participating in the pathogenesis of diabetic retinopathy." (PMID 32019593, 2020). "HMGB1 is involved in the pathogenesis of diabetic retinopathy through the combination of RAGE and TLR9." (PMID 30473885, 2018). "In this review, our focus is the important role of HMGB1 in inflammatory immune eye diseases, including keratitis, uveitis, dry eye, diabetic retinopathy, and retinal degeneration." (PMID 30473885, 2018). "In diabetic retinopathy, HMGB1 is closely related not only to the apoptosis of nerve cells but also to neovascularization; the latter involves STAT-3 as a downstream effector of HMGB1 to drive angiogenesis." (PMID 30473885, 2018). "HMGB1 is a multifunctional protein, and extracellular HMGB1 has been demonstrated to act as a pro-inflammatory factor in diabetic retinopathy." (PMID 26950148, 2016). "Little information exists on the relation of HMGB1 and miRNA in the cellular mechanisms of diabetic retinopathy." (PMID 26997759, 2016). "Recent reports have elucidated that HMGB-1 is involved in the pathogenesis of diabetic microvascular complications, including diabetic retinopathy." (PMID 25292258, 2014). "Recent studies have revealed an important role of inflammatory and proangiogenic high mobility group 1 (HMGB-1) cytokine in diabetic retinopathy." (PMID 24498140, 2014). "Recent studies have elucidated that HMGB-1 is involved in the pathogenesis of diabetic microvascular complications, including diabetic retinopathy." (PMID 24498140, 2014). "HMGB1 and the interplay with its ligands are illustrated in the process of several ocular diseases such as Aspergillus fumigatus keratitis, acute glaucoma, chronic autoimmune uveitis, and diabetic retinopathy." (PMID 35586052, 2022). "The enhanced B-wave amplitude could also be observed in an animal model of diabetic retinopathy, in which HMGB1 expression was diminished by treatment with siRNA." (PMID 35456925, 2022). "In animal models of diabetic retinopathy, a regulatory function of HMGB1 on the BRB is described." (PMID 34943212, 2021). "Together, these studies demonstrate that HMGB1 helps to drive diabetic retinopathy in two ways." (PMID 30473885, 2018). "Taken together, these findings suggest that additional work on HMGB1 and anti-HMGB1 agents may lead to novel therapies for some of the retinal complications of diabetic retinopathy." (PMID 28542588, 2017). "Previous studies have shown a correlation of HMGB1 to diabetic retinopathy." (PMID 26997759, 2016). "High-mobility group box-1 (HMGB1) is involved in the pathogenesis of diabetic microvascular complications, plays an important role in the inflammatory response, and its pro-angiogenic processes are closely associated with diabetic retinopathy." (PMID 26950148, 2016).